BRAF (B-Raf proto-oncogene, serine/threonine kinase)
Diseases named in the same sentence as BRAF in open-access papers (continued):
Sharing a sentence is not in itself a finding about the gene and the disease.
cancer (continued). "These MSI, BRAF mutated cancers have previously been well described as diploid, more commonly occurring in older females and the proximal colon, are often mucin producing and poorly differentiated." (PMID 23110075, 2012). "Cancers expressing oncogenic Ras display varying degrees of sensitivity to MEK inhibition with an overall low level of sensitivity to such inhibitors when compared to cancers harboring BRaf mutations." (PMID 22719838, 2012). "Whilst BRAF mutant/MSI cancers correlate with an excellent patient outcome, BRAF mutant/MSS cancers are associated with a very poor outcome that is even worse than the BRAF wild type/MSS cancers arising via the ‘traditional pathway’." (PMID 23110075, 2012). "Although there are multiple reports on the correlation of BRAF mutation with a variety of cancer progression steps, the correlation between BRAF mutation and cancer patient survival is still a matter of controversy in different reports." (PMID 23056577, 2012). "The presence of this BRAF mutation was associated with a significantly higher risk of dying from cancer-related causes, independently of other factors such as age, gender, PS, KRAS status, pathological finding, number of metastases, and metastatic sites." (PMID 22043994, 2012). "In summary, we used systematic review and meta-analysis approach to investigate possible association between BRAF-V600E mutation and cancer patient survival." (PMID 23056577, 2012). "Approximately half of these BRAF mutant cancers demonstrate frequent frameshift mutations termed microsatellite instability (MSI), but are diploid and chromosomally stable." (PMID 23110075, 2012). "Together, these reports nominate the BRAF-V600E mutation as a very promising therapeutic target in BRAF mutated cancers." (PMID 23056577, 2012). "In many cancers with BRAF mutations, the mutations are believed to be initiating events and also the driver mutations, but are not sufficient for complete neoplastic transformation." (PMID 21422497, 2011). "CIMP positive CRC cancers have distinct clinico-pathological features including proximal location, mucinous histopathology, female preponderance, and a high frequency of BRAF mutation." (PMID 21347319, 2011). "Epidermal growth factor receptor (EGFR) and its downstream factors KRAS and BRAF are mutated in several types of cancer, affecting the clinical response to EGFR inhibitors." (PMID 21943394, 2011). "In recent years, a plethora of promising compounds that target the RAS/RAF/MEK pathway have entered clinical trials, some of them demonstrating promising clinical activity, mainly in cancers with BRAF mutations." (PMID 22039425, 2011). "These cancers often show concurrent BRAF mutations and DNA CpG island hypermethylation (CIM), and associate with high-level DNA microsatellite instability (MSI-H) via methylation of the DNA mismatch repair gene hMLH." (PMID 21457162, 2011). "Concurrent data from the MSI analyses and the KRAS/BRAF mutation analyses were obtained in 74 carcinoma cases." (PMID 21457162, 2011). "A glutamic acid substitution for the valine at position 600 (V600EBRAF) accounts for over 90% of the mutations in BRAF in cancer." (PMID 20141835, 2010). "The prevalence of cancers with BRAF mutation was higher in females and in individuals with a later age at diagnosis, although these differences failed to reach statistical significance (both p = 0.07)." (PMID 20233436, 2010). "BRAF mutation was strongly associated with cancer of proximal colonic location, poor differentiation and microsatellite instability (all p < 0.001)." (PMID 20233436, 2010). "BRAF mutations are found in cancers with a clinicopathological signature of proximal colonic location, poor differentiation and microsatellite instability." (PMID 20233436, 2010). "KRAS and BRAF mutational frequencies were 19% and 43% in proximal carcinomas and 25% and 17% in rectal/sigmoid carcinomas, respectively." (PMID 20979647, 2010).
cancer (continued). "When considering the MSI-H carcinomas of the combined series, BRAF exon 15 mutations were detected in 17% of the rectal/sigmoid carcinomas and in 43% of those located elsewhere in the colon." (PMID 20979647, 2010). "In microsatellite stable (MSS) CRC BRAF mutations are rare and whenever present are associated with advanced carcinomas." (PMID 18782444, 2008). "One missense mutation in exon 15 resulting in a missense substitution, B-Raf p.V600E, accounts for over 90% of BRAF mutations identified in human cancer." (PMID 18060073, 2007). "Somatic activating mutations have been identified in multiple human cancers within these pathways, particularly in the BRAF and PIK3CA genes, respectively." (PMID 16822308, 2006). "Mutations in the BRAF gene derived from human cancer cell lines and human primary cancers can affect cellular transformation of NIH 3T3 cells, and Raf can exert tumorigenic effects independent of Ras." (PMID 15870716, 2005). "Whereas most BRAF mutations in human cancers involved V599 of BRAF, all of the four BRAF mutations in the NHLs involved other amino acids (one G468A, two G468R and one D593G)." (PMID 14612909, 2003). "However, the endoscopic features exhibited in d‐MMR/MSI‐H and BRAF‐mutated advanced cancer are unclear." (PMID 40548293, 2026). "Interestingly, this distribution of BRAF mutation classes in NSCLC, with a higher proportion of Class II and III mutations, differs from patterns typically observed in many other cancers where BRAF V600E (Class I) mutations predominate." (PMID 41282105, 2025). "For instance, mutations in Ras or BRAF (a Raf isoform) are common in many cancers." (PMID 39934876, 2025). "This difference may explain why BRAF mutations are prevalent in many types of cancers, whereas mutations in CRAF and ARAF are comparatively rare." (PMID 40890113, 2025). "A third example is the stratification of cancers caused by BRAF V600E mutations." (PMID 41294857, 2025). "Real-world overall survival by cancer type and by BRAF mutational classification." (PMID 40163685, 2025). "For cancers with activating BRAF mutations, various BRAF inhibitors are now available, such as vemurafenib, dabrafenib, and encorafenib, that selectively and competitively inhibit mutant BRAF and interfere with downstream MAPK signaling." (PMID 40076613, 2025). "Targets BRAF-mutated cancers; used in combination with trametinib for certain ovarian cancers." (PMID 40141188, 2025). "This precision is not only crucial for accurate diagnostic identification of genetic variations, such as single-nucleotide polymorphisms (SNPs) or disease-causing mutations (e.g., the BRAF V600E mutation in various cancers), but also underpins its utility in creating sophisticated disease models." (PMID 41149312, 2025). "Mutations in FGFR and BRAF disrupt this pathway, contributing to tumorigenesis in various cancers." (PMID 39907837, 2025). "The biologically relevant question we address herein is why there may be a differential response to BRAF inhibitors between two cancers in which a BRAF V600E mutation is the most frequent genomic driver observed." (PMID 40869231, 2025). "However, females have higher numbers when it comes to having BRAF gene mutation and right-sided cancers." (PMID 41311876, 2025). "Dabrafenib is a BRAF inhibitor primarily used to treat cancer with the BRAF V600E mutation." (PMID 40290445, 2025). "The diversity of BRAF mutations complicates cancer biology and poses treatment challenges." (PMID 41008893, 2025). "Autophagy may provide an alternative mechanism of cell death in cancer cells that have escaped apoptosis, and its inhibition may be effective especially in BRAF-mutated cancer cells." (PMID 40217782, 2025). "These dual pathologies underscore the importance of comprehensive genetic and molecular analysis, as shared mutations like RET or BRAF may drive their concurrent occurrence and be associated with other cancers." (PMID 40677447, 2025).
cancer (continued). "Oncogenic mutations in ARAF and CRAF also occur in cancer, though far less frequently than in BRAF." (PMID 41072765, 2025). "Recent genomic sequencings have identified over 300 BRAF mutations in various cancers." (PMID 39897565, 2025). "Moreover, some studies have associated BRAF V600E mutations with more aggressive disease and higher cancer-related mortality." (PMID 40075589, 2025). "BRAF mutations are associated with poor prognosis in cancer patients." (PMID 40896440, 2025). "Glu for Val substitution accounts for 90% of BRAF mutations in human cancers." (PMID 40872680, 2025). "BRAF V600E-positive tumours are cancers that carry a specific genetic mutation known as BRAF V600E." (PMID 40141188, 2025). "Somatic mutations in BRAF are a relatively common cause of cancer." (PMID 41072765, 2025). "However, the discovery of BRAF mutations in various cancers has revolutionized the treatment approaches and led to the development of targeted therapies that inhibit BRAF-mediated signal transduction." (PMID 41008893, 2025). "BRAF p.V600E is the most common BRAF mutation found in human cancers." (PMID 41175860, 2025). "Additionally, tissue samples from both the metastasis and primary carcinoma were examined for the BRAF V600E mutation using the RealLine BRAF Detect-V600E Kit (BIORON Diagnostics GmbH, Römerberg, Germany) following the manufacturer’s instructions." (PMID 40075771, 2025). "BRAF V600E mutations had the most significant effect on methylation levels at variant histone H2A.Z bound chromatin, a Roadmap Epigenomics annotation available for carcinoma cell lines and embryonic stem cells." (PMID 40102611, 2025). "The mutation V595E of canine BRAF is congruent with the V600E mutation in human cancer." (PMID 39591358, 2024). "When the BRAF gene mutates, it can lead to abnormal activation of the signaling pathway, which promotes cell proliferation, inhibits cell apoptosis, and ultimately contributes to the occurrence and development of cancer." (PMID 39529955, 2024). "EGFR and BRAF mutations exhibit a comparable frequency in human cancer." (PMID 38485987, 2024). "The spectrum of BRAF gene mutations is extensive, with over 30 mutations identified in human cancers, with the V600E mutation emerging as a prevalent driver mutation across multiple cancer types." (PMID 39156294, 2024). "The BRAF-mutated tumors also exhibited increased expression of several metabolic enzymes involved in the intracellular processing of anti-cancer drugs, which may lead to drug resistance and poor clinical efficacy." (PMID 38982444, 2024). "In addition, BRAF mutations occur in approximately 8% of cancers, which are very common in melanomas." (PMID 38193944, 2024). "In addition to cancer cells, nevi frequently harbor the BRAF V600E mutation, as evidenced by 82% of cases." (PMID 39200941, 2024). "The V600E mutation within the BRAF gene is of particular significance, as it has been closely linked with conditions like hairy cell leukemia, Lynch syndrome screening, and various cancers, including papillary thyroid carcinoma (PTC), colorectal cancer, melanoma, and non-small-cell lung cancer." (PMID 39156294, 2024). "In addition, patients with cancer, such as epidermal growth factor receptor-mutated nonsmall cell lung cancer or B-Raf proto-oncogene, serine/threonine kinase (BRAF)-mutated melanoma, inevitably acquire drug resistance after long-term treatment." (PMID 38429255, 2024). "LXH-254 demonstrated anti-cancer activity in tumors with BRAF/RAS co-mutations." (PMID 39056802, 2024). "BRAF hotspot mutations are oncogenic drivers in multiple cancer types." (PMID 38539548, 2024). "Thus, with the availability of tissue microarrays and IHC, large-scale screening of canine cancers by IHC for the presence of BRAF mutations has now become feasible." (PMID 38787171, 2024). "BRAF was mutated in a variety of cancers, leading to aberrant activation of the signaling pathway." (PMID 39239554, 2024).
cancer (continued). "BRAF-rearranged/mutated cases constitute 7% in cancer epidemiology." (PMID 39018206, 2024). "This cross-sectional study analyzes the largest dataset of BRAF-mutated cancers to date." (PMID 38275886, 2024). "Notably, the BRAF (V600E) mutation is prevalent across various cancers, making it a critical focus of contemporary research." (PMID 39500878, 2024). "The device was able to detect the BRAF V600E Mutation in cancer application successfully." (PMID 38542612, 2024). "In particular, miniprotein 76 impeded the phosphorylation of MEK1 explicitly in mammalian cells, implying that it could serve as a good starting point to develop new therapeutics for cancers caused by BRAF." (PMID 38791574, 2024). "Many cancer phenotypes, including those influencing response to therapy are in addition determined by non-genetic mechanisms in addition to genetic alterations such mutations/translocations concerning BRAF, ALK and NTRK." (PMID 38357207, 2024). "In addition, the discovery of third-generation inhibitors has aimed at preventing the dimerization of BRAF to overcome the resistance of the associated cancer cells to first- and second-generation inhibitors." (PMID 38791574, 2024). "Additionally, we reviewed clinical trials that led to the FDA approval of therapeutic regimens as monotherapy or, more recently, as combinatorial approaches to treat cancer types harboring BRAF hotspot mutations." (PMID 38539548, 2024). "Furthermore, the Wnt signaling pathway has been identified as a potential mediator of resistance to MEK inhibitors in cancers harboring somatic BRAF mutations, potentially driven by factors such as CEMIP." (PMID 39370455, 2024). "Interestingly, the cooccurrence of BRAF mutations and copy number gains was reported in human cancers." (PMID 38919805, 2024). "This approach seeks to achieve a synergistic effect by combining immunotherapy to enhance the immune system’s targeting of cancer cells, encorafenib to inhibit the cancer-driving BRAF V600E mutation, and cetuximab to target the often overactivated EGFR pathway in colorectal cancer." (PMID 38790167, 2024). "However, the genetic changes that distinguish these cancers extend beyond the single BRAF p.V600 mutation." (PMID 38667446, 2024). "In addition to point mutations, aberrant BRAF gene expression has been demonstrated in human cancers." (PMID 38919805, 2024). "Mutations within the BRAF gene can instigate disease via diverse mechanisms, encompassing inherited mutations that lead to birth defects and acquired mutations that contribute to the development of cancer as an oncogene." (PMID 39156294, 2024). "It ranks as the fifth most common cancer, with an estimated 100,350 new cases and 6,850 deaths in 2020, despite the use of modern systemic therapy such as checkpoint inhibitors and inhibitors of mutated BRAF V600E." (PMID 39618779, 2024). "Second, because the P+L combination can also work in BRAF V600E-mutated cancers, starting with L+P is an option if time is required for molecular profiling, especially considering that the growth of ATC is extremely rapid and that the possible clinical benefit can also be quite rapid." (PMID 39045273, 2024). "Notably, cancer cells with Kirsten ratsarcoma viral oncogene homolog (KRAS) or B-Raf Proto-Oncogene (BRAF) mutations show enhanced DHA absorption." (PMID 38792156, 2024). "Pathogenic BRAF mutations, which lead to the constitutive activation of the MPAK signaling cascade, are present in approximately 4% of all cancers, with the substitution of valine for glutamate at codon 600—BRAF V600E—accounting for at least 56% of all BRAF mutations and 70% of all PTCs." (PMID 39456495, 2024). "We investigated whether BRAF mutation class differed according to clinical, genomic, and transcriptomic variables in cancer patients." (PMID 38275886, 2024). "•Mutations in BRAF facilitate the occurrence and development of cancer." (PMID 39529955, 2024).
cancer (continued). "The ROAR (Rare Oncology Agnostic Research) trial is a multicenter, open-label, and phase II basket trial designed to evaluate the efficacy and safety of dabrafenib (oral BRAF inhibitor) plus trametinib (oral MEK inhibitor) for patients with rare cancers harboring BRAF V600E mutations." (PMID 39766138, 2024). "In this case, L was also used, although the cancer was BRAF V600E-mutated." (PMID 39045273, 2024). "This is supported by the absence of pyroptosis-related markers in BRAF and MEK-combined inhibition-resistant BRAF-mutant cancer models, which was associated with reduced T cell antitumor immunity and, importantly, was sensitive to pyroptosis-inducing chemotherapy." (PMID 38731852, 2024). "Results showed evident cytoplasmatic staining in BRAF-mutated cancer cells." (PMID 39591358, 2024). "This is the equivalent of the human BRAF p.V600E hotspot mutation in human cancers." (PMID 38787171, 2024). "BRAFV600E occurred more frequently in cancer tissues than benign nodules (92/124, 74.19% vs. 10/58, 17.24%, p < 0.0001), whereas BRAF mutations at other loci (such as the Raf-like Ras-binding domain) were detected primarily in benign nodules (10/58, 17.24% vs. 1/124, 0.81%, p < 0.0001)." (PMID 38886866, 2024). "Oncogenic mutations in BRAF are also seen at low frequencies in other cancer types." (PMID 38539548, 2024). "However, considering the high risk of recurrence in BRAF-mutant cancer, the patient continued on a combination therapy of encorafenib and cetuximab." (PMID 38962037, 2024). "Despite limitations due to low case numbers, a potential association between the dog’s breed and BRAF-mutated carcinomas could be observed." (PMID 39591358, 2024). "Furthermore, it has been shown that a BRAF mutation is significantly associated with increased carcinoma-related mortality." (PMID 39449865, 2024). "The SensiScreen® FFPE BRAF qPCR Assay will contribute to a more specific, time and cost saving approach to better identify and characterize mutations in patients affected by cancer, and consequently permits a better BRAF characterization that is fundamental for therapy decision." (PMID 36758042, 2023). "BRAF is frequently activated by the V600E mutation in many cancers." (PMID 38136350, 2023). "Of the Raf protein family, BRAF is most frequently implicated in cancer development." (PMID 37857607, 2023). "This includes the K57E variant that we identified in a single canine sample, which corresponds to the most frequently altered MAP2K1 codon identified in human cancers, and which has been associated with emergence of resistance to BRAF monomer inhibitors in human cancer cells." (PMID 37079639, 2023). "Interestingly, EGFR inhibitors have been identified to have an anti-cancer effect in cancer cells carrying BRAF mutation." (PMID 36658200, 2023). "BRAF mutations are related to approximately 8% of malignant tumors." (PMID 37153748, 2023). "Interestingly, more than 30 BRAF gene mutations have been found to be associated with human cancers." (PMID 37370792, 2023). "More than 30 mutations of the BRAF gene have been identified in association with human cancers." (PMID 38021761, 2023). "Combination therapy with MEK plus BRAF inhibitors could improve therapeutic outcomes in BRAF-mutated cancers and delay or prevent drug resistance, also be superior to monotherapy in terms of efficacy without significant increase in toxicity." (PMID 37808191, 2023). "There was no similar effect among AUS-other nodules (SEN: 46.2% vs. 46.2% vs. 7.7%, respectively), but it is difficult to draw unambiguous conclusions in this matter due to the very rare occurrence of BRAF mutations among cancers in this subcategory in our material." (PMID 37686562, 2023). "It was discovered in 2002 that BRAF mutations are present in certain human cancers." (PMID 38021761, 2023). "Indeed, PI3K genes and Ras genes mutations, PI3K genes and BRAF mutations, or PTEN and BRAF mutations often occur together in numerous cancer types." (PMID 37596643, 2023).